ALB (albumin)
Diseases named in the same sentence as ALB in open-access papers (continued):
Sharing a sentence is not in itself a finding about the gene and the disease.
Hypoalbuminemia (continued). "Considering that hypoalbuminemia is common in recipients after liver transplantation, this classification might not be appropriate for accurately estimating the effect of serum albumin on postoperative outcomes." (PMID 37167307, 2023). "Albumin replacement, therefore, seems reasonable in critically ill patients with hypoalbuminemia." (PMID 37218881, 2023). "Human albumin treatment can be used to treat hypoalbuminemia." (PMID 37034067, 2023). "Although the detrimental effect of preoperative hypoalbuminemia can be attenuated by active interventions, low serum albumin in the early postoperative stage is a common clinical scenario even for patients with normal serum albumin." (PMID 36803511, 2023). "When we limited our analysis to participants without hypoalbuminemia, we observed essentially the same association between serum albumin and height loss as that seen in the full sample." (PMID 37700384, 2023). "Second, albumin was administered at the discretion of the attending anesthesiologists, and the reasons for albumin administration, such as hypoalbuminemia and volume expansion, were unknown." (PMID 36768655, 2023). "Chi-square test and Fisher's exact test showed a significant association between the AKI stage (KIDGO) and the use of cement (p = 0.027), as well as between AKI stage (KIDGO) and postoperative hypoalbuminemia (defined as albumin levels lower than 25 g/L) (p = 0.031)." (PMID 37646924, 2023). "The presence of ascites in dogs from this study group was likely caused by hepatic portal hypertension rather than hypoalbuminemia, as all dogs with ascites had serum albumin levels greater than 2.3 mg/dL." (PMID 37627468, 2023). "Their findings also suggest that albumin may play a significant role in the protein-dependent response to oxidative stress during inflammation, and hypoalbuminemia may result in a reduction in plasma antioxidant capacity." (PMID 37628734, 2023). "Hypoalbuminemia is characterized as a secondary disease and includes increased capillary permeability, decreased protein synthesis, a reduced half-life, and increased total serum albumin." (PMID 36982882, 2023). "Recent cardiovascular procedures, preoperative shock status, thrombocytopenia (platelets < 100,000/uL), hypoalbuminemia (serum albumin < 2.8 g/dL), elevated serum ALT (≥ 100 U/L), and elevated serum creatinine (≥ 2.0 mg/dL) had significant impacts on 30-day mortality." (PMID 36890480, 2023). "Following adjustment for covariates in a multivariable logistic regression analysis, it was found that patients with hypoalbuminemia had a significantly higher incidence of postoperative UTIs compared to those with normal albumin levels (OR 1.86, 95% CI 1.28–2.70)." (PMID 37838687, 2023). "Therefore, hypoalbuminemia is frequently encountered during abdominal surgery, especially in patients receiving RBC transfusion due to transcapillary leakage of albumin, blood loss, and dilution from fluid resuscitation." (PMID 36768655, 2023). "Taken together, we do not know whether administration of BCAAs to NAFLD patients with hypoalbuminemia increases albumin levels or prolongs prognosis." (PMID 37432160, 2023). "Through that analysis, we observed that albumin infusions may lead to obvious benefits, significantly reducing mortality in hypoalbuminemia patients with SAP." (PMID 37277756, 2023). "The optimal cutoff values were 3.2 g/dL for albumin and 127 mg/dL for TG, with low areas under the curve of 0.69 and 0.76, respectively; however, the area under the curve for the combination of hypoalbuminemia and hypertriglyceridemia was considerably higher at 0.87." (PMID 37065302, 2023). "The centenarians who died had lower levels of albumin and higher prevalence of hypoalbuminemia." (PMID 37957767, 2023).
Hypoalbuminemia (continued). "The temporal response of albumin also appears to predict negative outcomes: individuals with hypoalbuminemia with a larger change in albumin on a second draw had fewer complications compared to those with hypoalbuminemia and a small change in albumin on repeat check." (PMID 37427016, 2023). "Among the 20 patients who developed subsequent LN, 23.5% of them had heavy proteinuria (urine protein > 3.5 g/day), 9/14 (64.3%) of them had documented hypoalbuminemia (serum albumin < 3.5 mg/dL), and 10% of them had an eGFR < 60 mL/min/1.73m2 at their LN diagnosis." (PMID 36964531, 2023). "Additionally, the median albumin level in all participants was 3.6 (3.2–4) g/dL, and hypoalbuminemia was observed in 32.9% subjects." (PMID 38140206, 2023). "SMID patients are known to induce hypoalbuminemia, and the serum albumin levels in our cases ranged from 3.1 to 4.5 mg/dL and may have partially influenced the overestimation of kidney function by eGFR-Cr." (PMID 37941705, 2023). "Albumin is also the primary transporter of drugs and metabolites and hence hypoalbuminemia may influence the pharmacokinetics of drugs used to treat severely ill patients thereby reducing its efficacy." (PMID 36996133, 2023). "Hypoalbuminemia is common in SMID and has various causes, including poor nutrition, decreased synthesis of albumin in the liver as a result of oral medications that affect liver metabolism, and excessive consumption of albumin due to acute or chronic inflammation." (PMID 37065302, 2023). "In addition, VARC-2 defined hypoalbuminemia (serum albumin < 3.5 mg/dL) as a criterion for frailty, closely related to nutritional status." (PMID 37763785, 2023). "Hypoalbuminemia is a surrogate marker of known disease processes present in advanced cancers, like increased catabolism, systemic inflammatory response, increased vascular permeability and interstitial edema, and decreased albumin synthesis." (PMID 37176111, 2023). "In our study, hypoalbuminemia was defined as serum albumin level <35 g/L during hospitalization." (PMID 37287379, 2023). "Only 4 (0.1%) patients showed hypoalbuminemia (albumin < 30 g/L)." (PMID 36747210, 2023). "This may be because patients need albumin infusion, which often means that the patient is in a state of hypoalbuminemia." (PMID 37770848, 2023). "As we only measured total posaconazole concentrations and our patient cohort presented with hypoalbuminemia (median albumin level of 18 g/dL), the free and therefore active fraction might have been higher." (PMID 37498488, 2023). "Hypoalbuminemia is defined by a serum albumin level below 35 g/L." (PMID 37892441, 2023). "It is unclear whether albumin infusion could improve the clinical prognosis of SAP with hypoalbuminemia, although SAP has many similarities to sepsis syndrome and septic shock." (PMID 37277756, 2023). "However, the high prevalence of low albumin in elderly nursing home residents is particularly worrying, as this study also showed a clear correlation between hypoalbuminemia and increased mortality." (PMID 37892441, 2023). "Therefore, we aimed to further verify the impact of hypoalbuminemia on the prognosis of SAP patients and the association between albumin infusions and mortality for hypoalbuminemia patients in this retrospective study." (PMID 37277756, 2023). "In addition, a small single-center randomized controlled trial published in 2006 showed a potential benefit of albumin administration in critically ill patients with hypoalbuminemia." (PMID 37764075, 2023). "Finally, CRS (odds ratio (OR) = 13.618, 95% confidence interval (CI) 1.499–123.709; P = 0.013) and baseline ALB (OR = 0.854, 95% CI 0.754–0.967; P = 0.020) were identified as the independent factors associated with post-CAR-T hypoalbuminemia." (PMID 37919691, 2023). "Albumin count (hypoalbuminemia) had a specificity of 83.18 (95% CI = 74.72–89.71%)." (PMID 36993799, 2023).
Hypoalbuminemia (continued). "Due to the cross-sectional nature of the observed association between frailty and hypoalbuminemia, it is not possible by means of the present analysis to disclose the causal or epiphenomenal role of poor albumin-levels in frailty with or without CKD." (PMID 35327615, 2022). "States of comorbidity that can lower serum albumin levels may contribute to hypoalbuminemia in the COVID-19 pandemic." (PMID 35507997, 2022). "Hypoalbuminemia is also a risk factor for AKI; therefore, serum albumin determinations might be useful to identify patients at increased risk for AKI." (PMID 35166177, 2022). "These measures may have helped improve nutrition and reduce severe hypoalbuminemia (serum albumin < 30 g/L) in the ERAS group." (PMID 35331289, 2022). "In addition, the predictive value of the GDF-15/albumin ratio was better than that of GDF-15 alone or other markers such as overhydration status or hypoalbuminemia proven by ROC analysis." (PMID 35204349, 2022). "Hypoalbuminemia is a typical trait of all severely ill patients and is often related to inflammatory diseases, mainly due to increased vascular permeability (with increased albumin distribution volume) and a shortened albumin half-life." (PMID 35956107, 2022). "As a result of defects in the albumin molecule and hypoalbuminemia, higher clearance and inability of adequate active transport of drugs, general drug intoxication, longer hospitalization, ineffective therapy, and high mortality might be observed." (PMID 36552520, 2022). "The possibility of hypoalbuminemia after operation in the low-risk group should not be ignored, thus, it is still necessary to pay close attention to the postoperative albumin value of the patients in this group." (PMID 35571899, 2022). "If hypoalbuminemia is both a prognostic indicator as well as a part of the pathophysiology of disease, perhaps albumin administration might then be part of the treatment in such patients." (PMID 35268297, 2022). "The observed decreased in serum levels of albumin (hypoalbuminemia) in our study may not only be due to decreased production but also due to hemodilution (i.e., resulting from hypervolemia) and proteinuria." (PMID 35836914, 2022). "Addition of albumin to the treatment, in cases of detection of hypoalbuminemia in intubated patients, may contribute to the recovery." (PMID 35507997, 2022). "Thus, the urine contains unwanted proteins (proteinuria) and blood cells (hematuria), while the bloodstream lacks enough protein albumin (hypoalbuminemia)." (PMID 36556986, 2022). "Furthermore, reduced albumin synthesis by the liver and increased microvascular permeability and consequent redistribution of albumin into extravascular compartments have also been suggested to contribute to hypoalbuminemia." (PMID 35223916, 2022). "Several investigators reported that hypoalbuminemia-induced low oncotic pressure might lead to a hypercoagulable state, which could be reversed by albumin infusion." (PMID 35123537, 2022). "Moreover, previous studies reported that hypoalbuminemia at the initiation of CRRT, as well as the dynamic changes of albumin during CRRT, are important risk factors for poor prognosis in AKI patients." (PMID 36112320, 2022). "The results of univariate analysis in our study showed that intraoperative albumin infusion did not increase the risk of postoperative pneumonia, indicating that a timely albumin infusion can be applied to correct hypoalbuminemia if necessary." (PMID 35875004, 2022). "Albumin binds approximately 15% of serum 25(OH)D; thus, hypoalbuminemia of critically ill patients could be responsible for approximately 15% of the variation 25(OH)D." (PMID 35745092, 2022). "Moreover, the median butyric acid level was lower in patients with hypoalbuminemia compared with those with normal albumin levels (below the limit of determination [LOD] vs. 220.87 μg/g; p < 0.05)." (PMID 36364889, 2022).
Hypoalbuminemia (continued). "Experimentally, LA reacted with albumin, calcium and induced hypocalcemia, hypoalbuminemia in mice." (PMID 35502320, 2022). "An inverse association between albumin and CVD may be explained by mechanisms related to the pathogenesis of CVD and inflammation associated with hypoalbuminaemia." (PMID 34980174, 2022). "The mechanism behind this phenomenon remains elusive; however, an inflammatory process may be involved, where the permeation of albumin into the interstitial space is promoted, eventuating in hypoalbuminemia." (PMID 36320896, 2022). "In the early stages, serum albumin deficits may be compensated for by the increased production of albumin molecules in the liver, which may prevent hypoalbuminemia." (PMID 36561389, 2022). "To study whether reduced production of albumin by the liver is responsible for hypoalbuminemia, we determined the hepatic expression of albumin by QPCR and Western blotting." (PMID 36232721, 2022). "Hypoalbuminemia may be a marker of comorbidity burden, a low serum albumin level may reflects an inflammatory burden leading to heart failure." (PMID 35706565, 2022). "Our group holds the view that the albumin loss portion in patients with preoperative albumin greater than or equal to 40 g/L is more than those with preoperative albumin of less than 40 g/L, however, it is not the main cause of postoperative hypoalbuminemia." (PMID 35571899, 2022). "A cut-off of 3.5 g/dl of albumin was used to define hypoalbuminemia in all except two studies." (PMID 36684211, 2022). "Thus, clinical study data suggest that hypoalbuminemia acts as an effect moderator in volume resuscitation and plasma expansion with IV human albumin solutions." (PMID 36430652, 2022). "It seems unreasonable that exogenous albumin is expensive to treat hypoalbuminemia." (PMID 36171266, 2022). "We have observed that hospitalized patients with hypoalbuminemia, regardless of their underlying disease tend to be sicker with a higher morbidity and mortality rate, than those with normal serum albumin levels." (PMID 35268297, 2022). "As 30% of plasma magnesium is bound to albumin, measuring total plasma magnesium may provide a spuriously low value in patients with hypoalbuminemia." (PMID 35739816, 2022). "Univariate analysis showed that hypoalbuminemia (an albumin level of < 25 g/L) and a white blood cell count of ≥ 15 × 103/μL were the laboratory parameters with a significant impact on CDI occurrence in COVID-19 patients (39.57% vs. 21.71%, p = 0.019 and 43.86% vs. 28.94%, p = 0.021, respectively)." (PMID 36143939, 2022). "Apart from this, all of the patients had hypoalbuminemia (albumin level of 1.93 ± 0.30 g/dL)." (PMID 35065599, 2022). "However, most previous studies have focused on the effect of the therapeutic use of albumin in patients who were already diagnosed with perioperative hypoalbuminemia." (PMID 35160076, 2022). "Prognostic value in GC patients was assigned to the albumin-fibrinogen relationship in serum, and we also found drastic concentration differences between sera of gastritis patients (hypoalbuminemia, high levels of fibrinogen), and those of all the other cases (V, NGM, U, GC), including MiGa." (PMID 35566209, 2022). "Additionally, albumin in plasma and water components potentially leaks into the interstitium, further contributing to hypoalbuminemia in patients with decompensated cirrhosis." (PMID 35581243, 2022). "Most consider hypoalbuminemia as serum albumin levels lower than 34 or 35 g/L." (PMID 35268297, 2022). "Grade 3-4 anemia, grades 3-4 thrombocytopenia, febrile neutropenia, and oral mucositis were significantly more frequent in HDMTX cycles with pre-infusion hypoalbuminemia than those with normal pre-infusion albumin (p=0.003, p=0.007, p=0.006, and p=0.001, respectively)." (PMID 35434757, 2022). "Albumin is the carrier for furosemide and hypoalbuminemia might result in decreased effect of the drug." (PMID 35696008, 2022).
Hypoalbuminemia (continued). "Psychiatric illness may influence the serum concentrations of albumin by altering daily behaviors such as ingestion; thus, hypoalbuminemia in patients with depressive disorders may be due to dietary deficiencies." (PMID 35395781, 2022). "It remains controversial whether exogenous albumin supplementation should be used to treat postoperative hypoalbuminemia in patients with STB." (PMID 35187165, 2022). "Albumin is a negative acute phase protein, and hypoalbuminemia has been associated with inflammation, cancer, and trauma." (PMID 36136714, 2022). "Because serum albumin level usually reduces after major abdominal surgeries, preemptive infusion of albumin can mitigate the decrease in serum albumin level and alleviate the influence of postoperative hypoalbuminemia." (PMID 35160076, 2022). "However, the incidence of hypoalbuminemia (serum albumin < 35 g/L) was similar between groups; a more effective perioperative nutritional support protocol is needed to improve their nutritional status." (PMID 35331289, 2022). "The mean albumin level was 3.8 ± 0.39 g/dL and 103 participants (68.7%) had hypoalbuminemia." (PMID 36579530, 2022). "In our study investigating the role of acute-phase reactants in the etiopathogenesis of COVID-19 pneumonia, the low serum albumin level in these cases makes us think that hypoalbuminemia may be a biomarker." (PMID 35507997, 2022). "Indeed, data regarding the necessity of perioperative albumin replacement in case of hypoalbuminemia remain scant and debated." (PMID 35164873, 2022). "An explanation for the association between albumin and DVT is that hypoalbuminemia may be a marker of inflammation, and inflammation can cause a hypercoagulable state in these patients." (PMID 35922845, 2022). "A 5-year follow-up of patients with systolic heart failure found a 2.2-fold higher risk of death from hypoalbuminemia (albumin ≤3.4 g/dl) compared to non-hypoalbuminemia [HR (95% CI), 2.2 (1.4–3.3)]." (PMID 36523355, 2022). "Adding albumin to the treatment may be effective in reducing mortality in cases of hypoalbuminemia, which we think may constitute a biomarker showing the severity of the disease." (PMID 35507997, 2022). "In this study, we successfully designed novel hydrogels based on low-methoxy pectin and NaA zeolite particles as a wound dressing material for either albumin adsorption from wounds with excess exudate or controlled albumin delivery to the wounded area for patients with hypoalbuminemia." (PMID 35160450, 2022). "Despite normalization of pre‐albumin levels, hypoalbuminemia slightly improved." (PMID 38868660, 2022). "A previous study reported that hypoalbuminemia was associated with 70% mortality risk, and this risk remained unchanged for those without normalisation of albumin." (PMID 35897315, 2022). "Although the exact contribution of fluid volume to serum albumin concentration was not analyzed due to the diversity of the fluid registered, the pattern of volume change after CRRT supported the possible role of dilutional hypoalbuminemia in the short-term serum albumin changes during CRRT." (PMID 35672868, 2022). "Some studies showed that preoperative replacement with exogenous albumin in patients with hypoalbuminemia could decrease the rate of acute kidney injury." (PMID 35164873, 2022). "Hypoalbuminemia reduces the amount of loop diuretic that is delivered to the tubular lumen so albumin infusion may help overcome diuretic resisteance." (PMID 37675009, 2022). "The co-existence of hypoalbuminemia and oxidative stress in many diseases may lead to the hypothesis that oxidative modifications of albumin decrease its detection and influence albumin quantification." (PMID 36077496, 2022). "Low serum ALB concentration or hypoalbuminemia was considered to be an indicator of prognosis after cardiovascular surgery and might be induced by congestive heart failure or chronic liver insufficiency." (PMID 34790710, 2021).